CAV3 (caveolin 3)
Diseases named in the same sentence as CAV3 in open-access papers (continued):
Sharing a sentence is not in itself a finding about the gene and the disease.
diabetes (13 papers, 2016 to 2025). "CAV3 is a muscle-specific isoform, and its dysfunction has been linked to various conditions, including diabetes, cancer, atherosclerosis, and cardiovascular disease." (PMID 36291131, 2022). "Caveolin-3 is a muscle-specific isoform, whose malfunction is associated with several diseases including diabetes, cancer, atherosclerosis, and cardiovascular diseases." (PMID 33228026, 2020). "Diabetes reduces association of caveolin-3 and eNOS in cardiomyocytes, an effect countered by antioxidant treatment." (PMID 29202762, 2017). "CAV3 (Caveolin 3) mainly encodes a protein of caveolin-3, which is mainly distributed in the membranes surrounding myocytes, and its dysfunction is associated with many diseases, including cancer and diabetes." (PMID 37328788, 2023). "Diabetes could cause inhibition of CAV-3 expression by regulating the activities of various enzymes and ion channels." (PMID 35329921, 2022). "This study determined whether the compromised RPC in diabetes was an independent manifestation of hyperglycemia-induced oxidative stress or linked to impaired Cav-3 expression with associated signaling abnormality." (PMID 31583053, 2019). "For the mechanisms involved, except the activated AMPK/Akt axis discussed earlier, RSV-induced Cav-3 enhancement was another mechanism triggering cardiac membrane Glut-4 translocation in diabetes, linked with the increased internalization of glucose in the cardiomyocytes in diabetes." (PMID 32256959, 2020). "However, it remains unclear whether the compromised RPC cardioprotection in diabetes is an independent manifestation of hyperglycemia-induced oxidative stress or linked to impaired Cav-3 expression and PI3K/Akt and JAK2/STAT3 signaling." (PMID 31583053, 2019). "However, it remains unclear whether or not excessive production of ROS mediated diabetic abnormalities is an independent manifestation of hyperglycemic injury or is linked to impaired Cav-3 expression and eNOS/NO signaling in diabetes." (PMID 27733157, 2016). "Specifically, long-term diabetes impairs the expression of Cav-3, leading to the silencing of multiple endogenous protective pathways, thereby ultimately weakening the protection of ischemic conditioning." (PMID 40012041, 2025). "Currently, studies have also found that some pharmacological conditioning strategies less affected by diabetes have potential link with Cav-3." (PMID 40012041, 2025). "Cav-3 is closely involved in insulin signaling, glucose metabolism and lipid homeostasis, dysfunction of which are common manifestation of diabetes." (PMID 40012041, 2025). "Recently, many studies have provided evidence that high fat diet-induced diabetes disrupted the expression of CAV-3, which deranged eNOS signaling in diabetic myocardium and then diminished the cardioprotective effects of APN." (PMID 35329921, 2022). "In the present study, decreased Cav-3 expression was detected in hearts from 5-week duration of diabetes, which is consistent with our previous studies." (PMID 31583053, 2019). "This notion is supported by our previous findings that decreased Cav-3 expression and cardiac NO bioavailability are detected in hearts from rats with chronic streptozotocin (STZ)-induced diabetes, which are associated with more serious myocardial I/R injury." (PMID 27733157, 2016). "Cav-3 is also involved in glucose uptake and thus affects the pathological course of diabetes." (PMID 40012041, 2025). "Cav-3 integrates and regulates a wide variety of signals to maintain cellular homeostasis, playing an important protective role in both myocardial I/R injury and diabetes." (PMID 40012041, 2025). "However, Cav-3 is significantly downregulated in diabetic hearts, whereas its cardiac-specific upregulation is shown to ameliorate diabetes-induced mitochondrial dysfunction via restoring the activity of mitochondrial complex I." (PMID 40012041, 2025).
diabetes (continued). "Thus, the depressed Cav-3 expression accompanied by reduction of GLUT-4 is likely to be the key pathological mechanism of diabetes." (PMID 40012041, 2025). "Conversely, decreased expression levels of CAV-3 were observed in diabetes animal models." (PMID 35329921, 2022). "Whether altered caveolin-3 interferes with the role of SF-PreCon in diabetes needs further investigation." (PMID 31913350, 2020). "However, in diabetes, the cardiac Cav-3 expression is impaired by hyperglycemia-induced oxidative stress, accompanied with lower activation of Akt and STAT3, while the diabetic hearts are more vulnerable to I/R injury and less responsive to RPC." (PMID 31583053, 2019). "The diabetes-induced decrease of Cav-3 expression may lead to caveola dysfunction, which plays a vital role in affecting PI3K/Akt and JAK2/STAT3 signaling in diabetic hearts." (PMID 31583053, 2019). "Although the precise mechanisms by which hyperglycemia-induced inhibition of Akt and STAT3 activation compromise RPC-induced cardioprotection are not fully understood, the reduced expression of Cav-3 during hyperglycemia in diabetes might be a major factor." (PMID 31583053, 2019). "Antioxidant treatment with NAC could restore RPC-induced cardioprotection in diabetes by improving Cav-3-dependent Akt and STAT3 activation and by facilitating the cross talk between PI3K/Akt and JAK2/STAT3 signaling pathways." (PMID 31583053, 2019). "The diabetes-induced decrease of Cav-3 expression may lead to caveolae dysfunction, which plays a vital role in affecting eNOS activity in diabetic hearts." (PMID 27733157, 2016). "We hypothesized that treatment with antioxidant N-acetylcysteine (NAC) could enhance cardiac Cav-3 expression and attenuate caveolae dysfunction and the accompanying eNOS/NO signaling abnormalities in diabetes." (PMID 27733157, 2016). "Diabetes-induced decrease of Cav-3 expression may lead to the reduced tolerance to myocardial I/R injury." (PMID 27733157, 2016). "Our data suggest that antioxidant treatment and improving Cav-3/eNOS signaling may be useful approaches for correcting diabetes-induced abnormalities." (PMID 27733157, 2016). "In this review, we outline the basic structure and function of Cav-3, emphatically present the unique role of Cav-3 as a signal integration and transduction element in diabetic myocardial I/R injury and discuss its therapeutic perspective in strategies against myocardial I/R injury in diabetes." (PMID 40012041, 2025). "Additionally, our further study has found that knockdown of Cav-3 by siRNA increases the levels of superoxide anion (O2•−) in cardiomyocytes, a main oxidizing substance during I/R, and improving Cav-3 expression attenuates ROS production and postischemic injury in diabetes." (PMID 40012041, 2025). "Moreover, caveolin-3 may play a pivotal role in 17β-estradiol (E2) actions on glucose metabolism, and there is evidence that E2 intervention reduces the incidence of diabetes." (PMID 35329921, 2022). "Furthermore, treatment of diabetes with antioxidant NAC reduced cardiac 15-F2t-IsoP, nitrotyrosine and O2− production, and enhanced the protein expressions of Cav-3 and eNOS and their association, and increased eNOS phosphorylation and NO levels to levels comparable to that in the control rats." (PMID 27733157, 2016). "Antioxidant NAC preserves RPC-induced cardioprotection by improving Cav-3-dependent Akt and STAT3 activation and by facilitating the cross talk between PI3K/Akt and JAK2/STAT3 signaling pathways in diabetes." (PMID 31583053, 2019). "Therefore, any alteration of Cav-3 expression in diabetes may be implicated in the compromised RPC-mediated cardioprotection, and thus, restoring Cav-3 expression should be beneficial to preserve the effectiveness of RPC in diabetes." (PMID 31583053, 2019).
diabetes (continued). "In summary, the current results demonstrate that hyperglycemia-induced oxidative stress is involved in the impaired Cav-3-modulated PI3K/Akt and JAk2/STAT3 signaling, which ultimately compromises RPC cardioprotection in diabetes." (PMID 31583053, 2019). "In the present study, HG exposure for 36 h decreased Cav-3 expression in isolated cardiomyocytes or H9C2 cells, which were consistent with deceased Cav-3 in hearts from 5 weeks duration of diabetes." (PMID 27733157, 2016). "Similarly, dexmedetomidine, a potent α-2 adrenergic receptor agonist, is shown to ameliorate myocardial I/R injury in the context of diabetes via stimulating PI3K/Akt pathway, a typical protective signaling modulated by Cav-3." (PMID 40012041, 2025). "We previously demonstrated impaired Cav-3 expression (a dominant constituent protein of cardiomyocyte caveolae formation) and reduced phosphorylation of Akt and STAT3 in diabetic hearts, which was attributable to decreased tolerance to myocardial I/R injury in diabetes." (PMID 31583053, 2019). "Although the precise mechanisms by which hyperglycemia-induced inhibition of eNOS activity causes adverse effects in diabetic myocardium are not fully clear, the decreased expression of Cav-3, which is simultaneously stimulated by hyperglycemia in diabetes, might be a major factor." (PMID 27733157, 2016).
Insulin resistance (13 papers, 2014 to 2025). Increased resistance towards insulin, that is, diminished effectiveness of insulin in reducing blood glucose levels. "Reduced expression of Cav-3 is associated with decreased glucose uptake and increased insulin resistance, which is a key pathological mechanism in the development of diabetes." (PMID 40362167, 2025). "Heterozygous Cav-3 mice show increased susceptibility to palmitae-induced insulin resistance, and loss of Cav-3 expression results in diabetic cardiomyopathy." (PMID 27733157, 2016). "This project will test the novel concept that a high‐palmitate diet disrupts caveolae function and thus contributes to impaired insulin signaling and insulin resistance through loss of IR regulation by CAV3." (PMID 27033451, 2016). "We further test whether haploinsufficiency for CAV3 increases the susceptibility to high‐fat‐induced insulin resistance." (PMID 27033451, 2016). "Recent studies have shown that damage to caveolin-3 (Cav-3) protein, which is found in cardiac muscle, plays a significant role in the development of insulin resistance." (PMID 40362167, 2025). "In a late phase, insulin resistance becomes apparent, accompanied by an impairment of caveolin-3 levels in skeletal muscle." (PMID 35329921, 2022). "Supporting the value of targeting caveolins, insulin-resistance in obese and DM mice is reversed by hepatic overexpression of caveolin-3, which substantially enhances InsR signaling." (PMID 29202762, 2017). "In CAV3 knockout mice, the IR protein in skeletal muscle decreased rapidly after 15 min of insulin stimulation, which led to the occurrence of insulin resistance, decreased glucose uptake and decreased glycogen synthesis." (PMID 29206848, 2017). "Researchers have found that CAV3-knockout mice develop insulin resistance in their skeletal muscles and that adenovirus-mediated gene transfer of CAV3 increases glycogen synthesis in the liver as well as improves insulin signaling in diabetic obese mice." (PMID 26674805, 2015). "There is evidence that increased CAV-3 expression contributed to GLUT4 translocation and thus ameliorated high-fat-diet (HFD)-induced glucose intolerance and insulin resistance, which indicated a positive correlation between the alternation of glucose metabolism and the level of caveolin-3." (PMID 35329921, 2022). "Moreover, high-fat-diet-fed animals showed metabolic alterations, obesity, and insulin resistance along with the induced expression of muscle-specific caveolin-3 in retroperitoneal adipocytes and skeletal muscle in the initial phase." (PMID 35329921, 2022). "Furthermore, mice null for caveolin-3 and caveolin-1 display insulin resistance, glucose intolerance and decreased insulin-induced glucose uptake; re-expression of these proteins reverses these conditions." (PMID 25914646, 2015). "Second, Cav-3 KO mice have a variety of deleterious phenotypes (i.e., muscle degeneration, insulin resistance, and progressive cardiomyopathy with age) that may affect outcome after ischemia/reperfusion injury." (PMID 25194961, 2014). "Cardiac insulin-resistance and impaired GLUT4 expression and transport in T2DM may involve disruption of caveolae and caveolin-3 with DM and high-fat feeding." (PMID 29202762, 2017). "Nonetheless, basal glucose metabolism appears largely unaltered in hearts lacking either caveolin-3 or caveolin-1, and thus also devoid of caveolae, although skeletal muscle insulin-resistance arises in both models." (PMID 29202762, 2017).
long QT syndrome (12 papers, 2008 to 2025). "Caveolin-3 is also associated with the α-subunit of the Nav1.5 ion channel, which has been suggested as the mechanism of CAV3-associated long QT syndrome or sudden infant death syndrome." (PMID 41144497, 2025). "CAV-3 is a novel Long QT syndrome (LQTS)-associated gene with mutations producing a gain-of-function, LQT3-like molecular/cellular phenotype, as a pathogenic basis of sudden infant death syndrome (SIDS)." (PMID 35329921, 2022). "The function of Cav-3 in Nav1.5 activity was further confirmed by evidence showing that mutations in specific Cav-3 sites were associated with dysregulated Nav1.5 activity and severe arrhythmias, such as long QT syndrome." (PMID 36229865, 2022). "Mutations in CAV3 cause several types of muscle related clinical diseases including muscular dystrophy, hypertrophic cardiomyopathy and the arrhythmia syndrome of Long QT syndrome (LQTS)." (PMID 30473666, 2018). "Mutations in Cav3 disrupt these signaling and coordinating microdomains and can cause structural cardiac and arrhythmic disease such as long QT syndrome (LQT9), sudden infant death syndrome, and hypertrophic cardiomyopathy." (PMID 30473666, 2018). "Mutations in the Cav3 gene have been found in patients with hypertrophic cardiomyopathy, long-QT syndrome, and muscular dystrophies." (PMID 27612189, 2016). "Recent studies have discovered mutations in CAV3 gene encoding caveolin-3 (Cav-3) in subject affected by hereditary arrhythmias - such as long QT syndrome (LQTS) and sudden infant death syndrome (SIDS) - or congenital cardiomyopathies." (PMID 24917393, 2014). "In the heart, caveolin-3 mutations are associated with hypertrophic and dilated cardiomyopathy and long-QT syndrome." (PMID 23585895, 2013). "Conduction of depolarization throughout the heart also appears dependent on caveolins, as Cav-3 KO animals display disorganization of the T-tubule complex, and mutations in the Cav-3 gene have been identified in patients with congenital long-QT syndrome." (PMID 23060817, 2012). "Mutations of SCN5A, CACNA1C and CAV3 are associated with ventricular tachycardia, long-QT syndromes (LQT3,8,9), and sudden cardiac death while mutations of HCN4 cause sick sinus syndrome type 2." (PMID 20300641, 2010). "CAV3 (LQT9): Mutations in CAV3 that encodes for caveolin 3 have been linked to a rare form of long QT syndrome designated as LQT9 which has been also been associated with sudden infant death syndrome (SIDS)." (PMID 18478063, 2008). "NaV1.5 regulatory proteins caveolin 3 (CAV3), alpha 1 syntrophin (SNTA1), and cardiac sodium channel beta subunit 4 (SCN4B) have been reported in association with rare subtypes of congenital long QT syndrome." (PMID 31336969, 2019).
hypertrophic cardiomyopathy (11 papers, 2009 to 2025). A condition in which the myocardium is hypertrophied without an obvious cause. "Knockout and loss‐of‐function mutations of Cav‐3 are associated with hypertrophic cardiomyopathy, further supporting a role for Cav‐3 as an inhibitor of cardiac hypertrophic signalling pathways." (PMID 30786093, 2019). "To date, there have been 30 caveolin-3 mutations identified in patients and one caveolin-3 mutant has been described in a case of hypertrophic cardiomyopathy." (PMID 22506041, 2012). "Specifically, CAV3 is of interest as it has been consistently associated with CHDs in reports that utilize more advanced tools and is closely related to cardiac development, through dilated and hypertrophic cardiomyopathies." (PMID 39841745, 2025). "For example, the hypertrophic cardiomyopathy caused by knockout of Cav-3 was associated with loss of caveolae and increased p42/p44 MAPK signaling whereas the cardiac-specific transgenic overexpression of Cav-3, as used in the present study, results in increased numbers of caveolar signalsomes." (PMID 29236992, 2018). "Mutations in the muscle-specific caveolin Cav3 cause at least five forms of muscle pathology, including limb girdle muscular dystrophy 1C, rippling muscle disease, distal myopathy, hyperCKemia, and hypertrophic cardiomyopathy." (PMID 24052812, 2013). "Knockout mice for caveolin-1, caveolin-2, and caveolin-3 develop hypertrophic cardiomyopathy with increase in fibrosis." (PMID 32626662, 2020). "Upon investigation, it was determined that this was associated with increased eNOS activity and showed that deregulation of Cav-3 within the heart can result in hypertrophic cardiomyopathy." (PMID 22934034, 2012). "Mice with overexpression of a P104L mutant of Cav-3, a model of autosomal dominant limb-girdle musclar dystrophy, showed mislocalization of Cav-3 and development of hypertrophic cardiomyopathy." (PMID 22934034, 2012). "CAV3 is also expressed in the cardiac muscle and, even if rare, cases of associations between mutations in its sequence with cardiac diseases have been reported, including long QT syndrome (LQTS), atrial fibrillation (AF), sudden infant death syndrome (SIDS) and hypertrophic cardiomyopathy (HCM)." (PMID 38256054, 2024).